CRP (C-reactive protein)
Diseases named in the same sentence as CRP in open-access papers (continued):
Sharing a sentence is not in itself a finding about the gene and the disease.
COVID-19 (continued). "Additionally, elevated levels of D-dimer, IL-6, and CRP in AIS patients with acute COVID-19 suggest that pre-stroke COVID-19 infection may contribute to increased secondary inflammation post-stroke onset." (PMID 38700338, 2024). "Besides cytopenia, several non-specific indicators linked with COVID-19-related sepsis, such as CRP, D-dimer levels, and lactate dehydrogenase are reported to be disturbed in cases of combined mucor infection, in addition to a dysfunctional renal profile." (PMID 38800245, 2024). "However, we observed a substantial increase in IL-6 and CRP levels associated with the severity of COVID-19, while no such trend was observed for IL-1β and TNF-α." (PMID 39188881, 2024). "Interestingly, in patients with COVID-19, an increase in CRP above 29.8 mg/L might indicate the presence of lung infiltrates." (PMID 39064460, 2024). "It is reported that a 44-year-old woman with COVID-19 was admitted to the hospital with complaints of chest pain; cardiac magnetic resonance and myocardial biopsy were suggestive of myocardial fibrosis, and normal CRP levels suggested that IL-6 was involved in this process." (PMID 39444690, 2024). "Multiple prognostic indicators have been proposed for COVID-19, including demographic factors, comorbidities, lung computed tomography (CT) findings, coagulation status, white blood cell counts, and inflammatory response biomarkers, such as C-reactive protein (CRP) and cytokines." (PMID 38741892, 2024). "Indeed, analysis of changes in the CSF proteome of patients with COVID-19 detected increased levels of C-reactive protein (CRP), upregulation of the complement system and coagulation cascade, and perturbed neuronal growth and signaling, cell adhesion, and macrophage activation." (PMID 38961383, 2024). "Interestingly, we found stimulated IL-6 performed better in diagnosing BRD compared to another study assessing both serum IL-6 and C-reactive protein (CRP) for diagnosis of severe COVID-19, for which an AUC of 0.82 and 0.74 and a YI of 63% and 42% respectively." (PMID 39541407, 2024). "In patients with COVID-19, the prognosis index for the course of the infectious process, CALC (comorbidity + age + lymphocyte + C-reactive protein), may represent a valuable marker for the risk assessment of primary development of mental disorders in the context of the underlying disease." (PMID 38426006, 2024). "The 4 CRP variants were chosen for their role in the innate immune system and availability in the SHS dataset, but no literature was found that examined CRP variants related to COVID-19 severity, perhaps because CRP has traditionally been viewed as a biomarker and not as a potential causal factor." (PMID 38662664, 2024). "Furthermore, another Iranian RCT with 60 ICU-admitted COVID-19 patients tested a combination of vitamins A, D, E, C, and B. This intervention led to significant improvements in serum vitamin levels and a decrease in C-reactive protein (p < 0.001)." (PMID 39195192, 2024). "In addition to that, elevated CRP was significantly associated with non-severe-to-severe aggravation of COVID-19, and the risk of advancing to the severe condition increased by five percent with a unit increase in CRP." (PMID 38610151, 2024). "In conclusion, tocilizumab accelerates the diminishing of CRP levels compared to standard treatment alone, and its use may have potential benefits in the management of severe COVID-19 patients when used alongside with follow-up quantification of CRP levels reduction." (PMID 38687065, 2024). "In our model, based on a high level of CRP, increased neutrophil, low lymphocytes, and low albumin, patients with a high level of D-dimer were with a higher mortality, indicating that the measurement of D-dimer is helpful for COVID-19 prediction, which is consistent with previous findings." (PMID 38698064, 2024). "Furthermore, CRP and ferritin differed significantly between moderate vs. severe COVID-19 cases." (PMID 38183501, 2024).
COVID-19 (continued). "In conclusion, we have demonstrated that elevated mSOFA score, D-dimer, CRP, WBC count and decreased platelet count on day 1 of admission were associated with higher 30- and 60-day mortality, higher ICU transfer and more overall mortality among hospitalized COVID-19 patients." (PMID 37934759, 2023). "Therefore, it is still controversial whether the increase of CRP in the early stage of COVID-19 can be used as a prognostic indicator." (PMID 37990060, 2023). "Of the 90 patients, 84 (93.3%) diabetic/hypertensive patients had severely high levels of CRP (>10 mg/dL), of whom 67 (79.8%) were admitted to ICUs and 17 (20.2%) to wards, and six (6.7%) patients had moderately high CRP levels (1-10 mg/dL) and were admitted to COVID-19 isolation wards and ICUs." (PMID 38022228, 2023). "The differing roles of the pentameric (p) and monomeric (m) C-reactive protein (CRP) isoforms in viral diseases are not fully understood, which was apparent during the COVID-19 pandemic regarding the clinical course of severe acute respiratory syndrome coronavirus 2 (SARS-CoV-2) infection." (PMID 37724104, 2023). "Thus, this may have been a source of bias when interpreting the value of CRP, which is elevated in COVID-19 patients." (PMID 37510110, 2023). "As all of these parameters can be measured and analyzed rapidly, and BUN and CRP are relatively inexpensive, the such composition of the predictors may be highly efficient for the triage of patients with severe COVID-19 in the ICUs if applied in a neural network context." (PMID 36826535, 2023). "In addition, CRP and ferritin levels were negatively correlated (P<0.05), which implies that CRGs may influence COVID-19 progression through lactate metabolism and ferritin metabolism." (PMID 37533853, 2023). "This study aimed to determine whether clinical findings, symptoms, and parameters that are cost-effective and available in many clinics such as C-reactive protein (CRP) lymphocyte ratio (CLR), and ferritin CRP ratio (FCR) can be used in the diagnosis of PE in patients with COVID-19." (PMID 37653759, 2023). "In patients with COVID-19, a moderate positive correlation was found between glycaemia and the percentage of neutrophils (r = 0.32, p = 0.005), and a weak positive correlation was found between glycemia and CRP (r = 0.254, p = 0.034) and total leucocytes (r = 0.284, p = 0.016)." (PMID 37241176, 2023). "However, the rapid prognosis of COVID-19 using routine markers such as complete blood count or C-reactive protein might be a cost-efficient solution for developing and least-developed countries in case of pandemics caused by other SARS-CoV-2 mutants." (PMID 36826535, 2023). "However, in older COVID-19 patients more and stronger correlations could be detected with hs-CRP (all p < 0.01): IL8 (r = 0.548), MCP3 (r = 0.720), CXCL10 (r = 0.460), CCL23 (r = 0.577) and IL6 (r = 0.706)." (PMID 37832397, 2023). "In patients with severe forms of COVID-19 also a strong relationship between early overexpression of IL-10 and increased serum concentrations of IL-1 receptor antagonist (IL-1RA) and other proinflammatory molecules, including IL-6, IL-8 and C-reactive protein was observed." (PMID 37359549, 2023). "Thus, CRP can be considered one of the possible markers of the severe course of COVID-19." (PMID 37545134, 2023). "Traditionally, CRP has been used as a systemic clinical marker of inflammation in COVID-19 and other diseases, although the SROC curves suggest that other acute phase proteins, such as ORM1, CRTAC1, SERPINA3, TF, and AHSG might perform better as biomarkers of inflammation." (PMID 37739942, 2023). "However, uric acid level was inversely associated with CRP level, and the association between the level of uric acid and severe COVID-19 progression was significantly different with and without CRP level inclusion." (PMID 36979833, 2023).
COVID-19 (continued). "Several risk factors associated with the development of severe disease in pediatric patients with COVID-19 have been described, including age (under 5 years and adolescents); previous comorbidities; symptoms of cough, dyspnea and fever on admission; and lymphopenia, elevated CRP and LDH." (PMID 37892366, 2023). "Despite elevation of CRP in critical COVID-19 patients, but our regression model didn't support its use as predictor for mortality, this finding is in contrast to Huyut MT, Ilkbahar F and Xie Jet al. who displayed that CRP was an important predictor for the progression of COVID-19 disease." (PMID 36999046, 2023). "Understanding the mechanisms underlying the positive correlation between CRP and megakaryocytes, as well as the role of the CRP-SPARC interaction, could provide valuable insights into the pathogenesis of COVID-19 and potentially identify novel therapeutic targets." (PMID 38077346, 2023). "In addition, COVID-19 severity was associated with the ACE D/D genotype and with high CRP levels." (PMID 37238156, 2023). "In addition, high levels of some biomarkers, such as C-reactive protein, D-dimer, procalcitonin, and ferritin, in individuals with multiple comorbidities may lead or contribute to a worse prognosis of COVID-19." (PMID 36626821, 2023). "Likewise, our previous results revealed that lowered SpO2 in the acute phase predicted lowered Gpx and increased NO production in long COVID patients and that elevated BT during acute COVID-19 predicted increased CRP and lowered antioxidant defenses, including zinc, in long COVID." (PMID 36675440, 2023). "However, how did CRP participated in the COVID-19 pathogenesis remains poorly understood." (PMID 38077346, 2023). "Similarly, CRP was also higher in patients with severe COVID-19 (68 vs. 124 mg/L, p < 0.001)." (PMID 36983064, 2023). "Similarly, our study demonstrated that in healthy and high-risk hosts, 14.8% of nonsevere cases had persistently high CRP levels (≥ 5 mg/L) 6 months after COVID-19." (PMID 37653091, 2023). "Therefore, the correlation between CRP and the prognosis of COVID-19 infection is controversial, and most of the previous similar studies had small sample sizes, and rarely analyzed the curve fitting relationship between CRP and the mortality rate of COVID-19 patients." (PMID 37990060, 2023). "Moreover, elevated CRP has been used as a predictor of COVID-19 severity and mortality." (PMID 38003780, 2023). "This suggests that CCP therapy may reduce CRP levels in patients with COVID-19." (PMID 37754308, 2023). "In addition, the association of serum uric acid level with severe COVID-19 progression was significantly different with and without inclusion of serum CRP, but not of serum KL-6 or plasma D-dimer level." (PMID 36979833, 2023). "Routine laboratory blood tests, including Eosinophils (EO), C-reactive protein (CRP), interleukin 6 (IL-6), Prothrombin time (PT), and lactate dehydrogenase (LDH), have been implicated in the pathogenesis of COVID-19 and are used as indicators of disease severity." (PMID 38094227, 2023). "Indeed, recent studies have reported that elevated CRP together with higher D-Dimers and fibrinogen serum levels characterize the hyperinflammation and hypercoagulable states seen in severe and/or deceased COVID-19 patients." (PMID 37388734, 2023). "Consequently, this much greater percentage of Roma patients with severe COVID-19 who had increased IL-6 levels at admission might explain why these patients also had persistently elevated inflammatory markers, such as CRP and ESR, upon admission." (PMID 36836429, 2023). "This may be caused by the mild course of COVID-19, low number of enrolled subjects, and by the fact that children with a higher CRP level were not included in the study." (PMID 37241176, 2023). "Furthermore, our results showed that both 2 doses and 3 doses of the COVID-19 vaccine could inhibit CRP levels in the asymptomatic and the mild groups." (PMID 37217986, 2023).
COVID-19 (continued). "Furthermore, data showed that aspartate transaminase (AST), alanine transaminase (ALT), LDH, total creatine kinase (CK), myoglobin (MGB), ferritin, CRP, and D-dimer could all be considered strong early predictors of COVID-19’s severity and death." (PMID 37110348, 2023). "Furthermore, serum CRP, but not serum KL-6 or plasma D-dimer level, had an influence on the association between serum uric acid level and severe COVID-19 progression." (PMID 36979833, 2023). "In the present study, evaluation of laboratory results of patients with CAD and COVID-19 revealed that there was a change in some important laboratory factors, including increased D-dimer, increased troponin, increased ferritin, and also an elevation in CRP levels." (PMID 37275509, 2023). "Interestingly, CRP increased by 86.22% in patients with COVID-19." (PMID 36687389, 2023). "In addition, the best predictor of mortality in COVID-19 patients is CRP." (PMID 37484181, 2023). "Before D0, CRP kinetics showed a significant increase in infected patients, whereas in noninfected it remained almost unchanged (p < 0.001), while PCT kinetics did not appear to retain diagnostic value to predict superinfection in COVID-19 patients (p = 0.593)." (PMID 37834754, 2023). "Firstly, although CRP is an established marker in the management of infections, it is non-specific for viral infections, and the notion of a new and potentially more comprehensive biomarker, such as LCR, for risk stratifying COVID-19 patients is highly desirable." (PMID 37373898, 2023). "Although the number of included studies was minimal, this meta-analysis suggests that NAC may have a positive effect on COVID-19 outcomes, specifically, a significant decrease in CRP and D-dimer levels and a significant increase in oxygen saturation, which decreased mortality." (PMID 37534078, 2023). "Such alteration was found to negatively correlate with C-reactive protein, lactate dehydrogenase, and partial oxygen pressure and to positively correlate with partial carbon dioxide pressure, thus promoting disordered oxygen hemostasis and lung damage in COVID-19 patients." (PMID 37587394, 2023). "However, an inverse association of uric acid level with CRP level was noted, while the association between uric acid level and progression to severe COVID-19 was significantly different with and without its inclusion." (PMID 36979833, 2023). "Inflammatory markers and pro-inflammatory cytokines, such as CRP, ferritin, IL-1β, IL-8, TNF-α, and MCP1, show a significant increase in their serum concentrations, and the elevated neutrophil-to-lymphocyte ratio is associated with more severe cases of COVID-19 that can lead to death more easily." (PMID 37408184, 2023). "Although CRP levels are elevated in COVID-19 patients, studies have demonstrated a clear association between illness severity and prognosis: survivors (Moderate and Severe) had median CRP values of about 40 mg/l, whereas non-survivors (Critical) had median rates of 125 mg/l10." (PMID 37363608, 2023). "It is possible that CRP, ferritin, and fibrinogen may be more specific to COVID-19." (PMID 38222192, 2023). "Although higher BMI has been clearly associated with worse COVID-19 outcomes, it is unknown whether the risk is due to increased “classical-signaling” activity, independent of adipose tissue-induced CRP release, or other inflammatory cascades." (PMID 38003780, 2023). "Although both ESR and CRP are inflammatory markers that could increase in other infectious diseases, e.g., TB, their inclusion in the CoMPred indicator increased its sensitivity to predicting mortality among COVID-19 patients." (PMID 37893025, 2023). "Elevated CRP could be due to bacterial coinfection that may occur in severe COVID-19." (PMID 38027038, 2023).
COVID-19 (continued). "Uncontrolled exploratory study showed that nebulized IFN-α2b in adult patients hospitalized with COVID-19 significantly reduced the duration of the detectable virus in the upper respiratory tract and duration of elevated levels of inflammatory markers (IL-6 and CRP) in the blood." (PMID 37240213, 2023). "Finally, there was a significant increase in CRP, ferritin and D-dimer in severe and moderate COVID-19 patients compared with controls (P2 < 0.001, P3 < 0.001) and a significant increase in CRP (P1 = 0.044) and ferritin (P1 = 0.03) in severe COVID-19 patients compared to moderate COVID-19 patients." (PMID 37653506, 2023). "Therefore, it is important to monitor changes in CRP levels in COVID-19 patients." (PMID 37720137, 2023). "Laboratory results suggested that when infected with COVID-19, the PD patients experienced a heightened inflammatory response, including higher white blood cell count and neutrophil count, lower lymphocyte count, a higher neutrophil/lymphocyte ratio (N/L) and CRP levels." (PMID 37213541, 2023). "Altered levels of C-reactive protein (CRP), neutrophil and lymphocyte counts, ferritin, D-dimer, and lactate dehydrogenase, as well as a high CO-RADS score and the presence of some abnormal chest CT findings have been associated with the presentation of severe complications of COVID-19." (PMID 37746553, 2023). "Periodontal disease seems to be associated with a higher risk of COVID-19 complications, including intensive care unit (ICU) admission, assisted ventilation, death, and serum increase in markers of COVID-19 worsening, including D-dimer, white blood cells (WBC), and C-reactive protein (CRP)." (PMID 35224542, 2022). "Suggested as a biomarker to rule out bacterial complications/co-infections in patients with COVID-19 at the onset of the pandemic, C-reactive protein later proved to have low diagnostic value, being non-specific for bacterial infection and elevated in many hospitalized patients with COVID-19." (PMID 35622702, 2022). "Furthermore, in addition to the increase in D-dimer (which is also an acute-phase protein that rises with general inflammation) an increase in inflammatory biomarkers such as CRP, particularly in COVID-19 patients with a more severe disease phenotype, is also seen." (PMID 35867647, 2022). "Collectively, these results reveal that the increase of hyaluronan is significantly relevant to the reduction of lymphocytes and the upregulation of CRP, D-dimer, and fibrinogen in COVID-19 patients, suggesting hyaluronan may play a key role during the clinical progression of COVID-19." (PMID 35304437, 2022). "A previous meta-analysis demonstrated that severe COVID-19 is closely associated with a decrease in lymphocytes and lymphocyte subsets, as well as the elevation of C-reactive protein (CRP), procalcitonin (PCT), and cytokines, but not interleukin (IL)-1β and IL-17." (PMID 35346253, 2022). "Furthermore, according to previous studies, neutrophilia, lymphopenia, elevated CRP and male gender may predict liver damage in COVID-19 patients." (PMID 36556915, 2022). "This could explain the hematological findings in COVID-19 severe cases including leukocytosis, lymphopenia, thrombocytopenia, neutrophilia, elevations in erythrocyte sedimentation rate, C-reactive protein (CRP), IL-6, fibrinogen, ferritin, lactate dehydrogenase, and D-dimer." (PMID 35408447, 2022). "To examine whether NP, CRP, and IL-6 were produced through the same signaling pathway in viral infection (COVID-19 patients) and other causes (non-COVID-19 patients), we analyzed their correlations." (PMID 35529699, 2022). "The presence of leukocytosis, lymphopenia, thrombocytosis, elevated systemic inflammatory index and neutrophil-lymphocyte ratio, hyponatremia, hypochloremia and elevated levels of AST, ALT, LDH and CRP may help healthcare providers in early identification of COVID-19 patients." (PMID 35976368, 2022).